DYSF (dysferlin)
Description:
Key calcium ion sensor involved in the Ca(2+)-triggered synaptic vesicle-plasma membrane fusion. Plays a role in the sarcolemma repair mechanism of both skeletal muscle and cardiomyocytes that permits rapid resealing of membranes disrupted by mechanical stress (By similarity).
Synonyms: FER1L1; LGMD2B; LGMDR2; MMD1
Tractability: Antibody: its Gene Ontology location is reachable by antibodies, with high confidence; UniProt places it where antibodies can reach, with medium confidence; UniProt predicts a signal peptide or a membrane-spanning region. PROTAC: ubiquitination databases record sites on it; its protein half-life has been measured.
Gene: Protein-coding gene on chromosome 2 (71,453,561 to 71,686,763, forward strand). Ensembl gene ENSG00000135636.
Subcellular location: Cell membrane, sarcolemma; Cytoplasmic vesicle membrane; Cell membrane; Late endosome membrane
Subcellular location (Human Protein Atlas): Centriolar satellite; Mid piece; Plasma membrane
Pathways (Reactome):
Muscle contraction: Smooth Muscle Contraction
Gene Ontology:
Molecular function: calcium ion binding; calcium-dependent phospholipid binding; phospholipid binding; protein binding
Biological process: macrophage activation involved in immune response; monocyte activation involved in immune response; negative regulation of phagocytosis; regulation of neurotransmitter secretion
Cellular component: early endosome; endocytic vesicle; endosome; extracellular exosome; late endosome; late endosome membrane; plasma membrane; sarcolemma; T-tubule; cytoplasmic vesicle membrane; synaptic vesicle membrane; membrane
Genetic constraint (gnomAD): Loss-of-function variants: 211 observed, 282.82 expected, observed/expected ratio (o/e) 0.75, 90% interval 0.67 to 0.84. The upper end of that interval is the gene's LOEUF score, 0.84, which puts it in group 3 of 6, group 1 being the genes least tolerant of losing a copy. Missense variants: 2,666 observed, 2,871.1 expected, observed/expected ratio (o/e) 0.93, 90% interval 0.9 to 0.96. Synonymous variants: 1,091 observed, 1,118.7 expected, observed/expected ratio (o/e) 0.98, 90% interval 0.93 to 1.02.
Gene-disease validity (ClinGen):
ClinGen rates the evidence that DYSF causes each of these diseases.
autosomal recessive limb-girdle muscular dystrophy (autosomal recessive): Definitive. Autosomal recessive form of limb-girdle muscular dystrophy.
Homologues: Orthologues: chimpanzee DYSF (99% identical), macaque DYSF (97% identical), rat Dysf (94% identical), dog DYSF (93% identical), pig DYSF (93% identical), rabbit DYSF (93% identical), guinea pig DYSF (93% identical), mouse Dysf (93% identical), tropical clawed frog DYSF (73% identical), zebrafish dysf (67% identical), Drosophila melanogaster mfr (19% identical). Paralogues in human: MYOF (55% identical), FER1L5 (40% identical), OTOF (32% identical), FER1L6 (30% identical).
Diseases named in the same sentence as DYSF in open-access papers:
DYSF is named in the same sentence as 129 diseases in open-access papers, as found by Europe PMC text mining. Sharing a sentence is not in itself a finding about the gene and the disease. The quoted sentences say what the papers report.
dysferlinopathy (135 papers, 2007 to 2026). "Dysferlinopathies are a subset of autosomal recessive muscular dystrophies resulting from pathogenic variants in the dysferlin (DYSF) gene." (PMID 41677014, 2026). "Dysferlinopathy is an adult-onset form of muscular dystrophy caused by mutations in the dysferlin gene and is inherited in an autosomal recessive manner." (PMID 41824290, 2026). "The DYSF-R1925X mouse is a newly designed mouse model for dysferlinopathy inspired by the human R1905X mutation in the DYSF gene." (PMID 41584851, 2026). "Dysferlinopathies comprise a group of rare muscle disorders caused by pathogenic variants in the DYSF gene that result in a broad spectrum of clinical phenotypes and disease severities." (PMID 39936969, 2025). "In Mexico, a study confirmed a variant in the DYSF gene classified as pathogenic or likely pathogenic, thereby confirming dysferlinopathy in a Mexican family from an endogamous region." (PMID 41200659, 2025). "Dysferlinopathies are rare autosomal recessive diseases caused by pathogenic variants in the DYSF gene that result in a significant reduction or complete absence of the dysferlin protein." (PMID 39936969, 2025). "Dysferlinopathy caused by mutations in the DYSF gene is located on the short arm of Chromosome 2 (2p13)." (PMID 40740503, 2025). "The morpholino knockdown zebrafish model was used to understand the underlying mechanism of dysferlinopathy and the dysferlin protein’s role in the stabilization of muscle structure and sarcolemma repair." (PMID 41009401, 2025). "Mutations in the DYSF gene cause a set of muscular dystrophies collectively known as dysferlinopathies, including limb–girdle muscular dystrophy type 2B (LGMDR2) and Miyoshi myopathy (MM)." (PMID 41155239, 2025). "Dysferlinopathy is caused by over 500 mutations in the gene encoding dysferlin, including close to 300 point mutations." (PMID 40565111, 2025). "Dysferlinopathies refer to a group of rare, recessively inherited muscular dystrophies that are caused by mutations in the dysferlin gene (DYSF), leading to a deficiency or dysfunction of the dysferlin protein." (PMID 40021220, 2025). "Exon skipping, mediated through antisense oligonucleotides (ASOs), is a promising approach to exclude pathogenic variants from the DYSF gene and treat dysferlinopathies." (PMID 39936969, 2025). "For currently untreatable dysferlinopathy, exosomes from myotubes or human serum act as potent nanocarriers, delivering full-length dysferlin gene/protein to deficient fibers and restoring dysferlin expression, offering a novel therapeutic avenue." (PMID 40868246, 2025). "Less commonly, DYSF variants can also result in other dysferlinopathies such as distal myopathy with anterior tibial onset (DMAT), the proximodistal phenotype, and asymptomatic hyperCKemia." (PMID 39936969, 2025). "In this article, prime editing is used to correct several point mutations in the DYSF gene responsible for dysferlinopathy." (PMID 40565111, 2025). "Dysferlinopathies are progressive muscular dystrophies caused by DYSF mutations, leading to impaired membrane repair, chronic inflammation, lipid accumulation, and muscle degeneration." (PMID 41155239, 2025). "Dysferlin-deficient proximo-distal phenotype occupies a unique position in the spectrum of dysferlinopathies, nestled between LGMDR2 and MM." (PMID 38540676, 2024). "Subsequently, we examined the correlation between the expression of key proteins and the clinical characteristics of the patients to identify pathogenic targets associated with DYSF mutations in dysferlinopathy." (PMID 39350328, 2024). "Similar to the human DYSF variant p.Leu1341Pro, this particular variant induces all the characteristics of a dysferlinopathy arising from a missense mutation, including progressive muscular dystrophy, amyloid formation, and defects in membrane repair." (PMID 38891760, 2024).
dysferlinopathy (continued). "Mutations in DYSF observed in patients with dysferlinopathy result in decreased expression of its protein in skeletal muscle." (PMID 39350328, 2024). "Validating the effects of the two de novo mutations in DYSF on dysferlin protein expression, localization, structure, and function in vivo and in vitro was important to reveal the pathogenic mechanism of dysferlinopathy." (PMID 38903757, 2024). "The pathogenic mechanism of aberrant splicing in dysferlinopathy due to two homozygous adjacent missense mutations in the DYSF gene was determined by an in vivo splicing assay and an in vitro minigene assay." (PMID 38903757, 2024). "Because these phenotypes are close to and easily confused with other causes of muscular dystrophy, clinical diagnosis of dysferlinopathy requires a combination of isoferrin deficiency in the blood and genetic testing to detect DYSF mutations." (PMID 38903757, 2024). "Dysferlinopathies, recessively inherited muscular dystrophies, stem from mutations in the dysferlin gene (MIM#603009, GenBank NM_003494.2)." (PMID 39350328, 2024). "These conditions are collectively known as dysferlinopathies and are caused by more than 600 mutations that have been identified across the DYSF gene to date." (PMID 38891760, 2024). "The discovery of heterozygous mutations in the DYSF gene provided robust evidence supporting the diagnosis of dysferlinopathy." (PMID 39911674, 2024). "We examine the phenotypic heterogeneity of dysferlinopathies, highlighting the incomplete understanding of genotype-phenotype correlations and discussing the implications of various DYSF mutations." (PMID 38540676, 2024). "Dysferlinopathies manifest a marked inflammatory signature, indicative of disrupted immune responses in dysferlin-deficient muscles." (PMID 38540676, 2024). "The development of effective therapies for dysferlinopathy is hindered by the mild disease symptoms in dysferlin‐deficient mouse models." (PMID 38887849, 2024). "Dysferlinopathy is a phenotypically heterogeneous group of hereditary myopathies caused by mutations in the DYSF gene that has been mapped to locus 2p13.3-13.1." (PMID 38365661, 2024). "The detection of dysferlin deficiency in muscle tissue or blood and along with the identification of mutations in the DYSF gene, are the primary methods for diagnosing dysferlinopathy." (PMID 39911674, 2024). "In a cohort of 300 Indian patients diagnosed with LGMD, dysferlinopathy was determined in 33% of cases based on the detection of deficient DYSF protein levels." (PMID 38539162, 2024). "Dysferlin-associated asymptomatic hyperCKemia, often termed isolated hyperCKemia, stands out as a unique and rare clinical variant within the spectrum of dysferlinopathies." (PMID 38540676, 2024). "Dysferlinopathy is an autosomal recessive inherited skeletal muscle disorder caused by a mutation in DYSF, resulting in abnormal dysferlin protein expression." (PMID 38903757, 2024). "Dysferlinopathy is a phenotypically heterogeneous group of hereditary diseases caused by mutations in the DYSF gene." (PMID 38365661, 2024). "These outcomes support potential treatment of DYSF nonsense mutations, providing hope for dysferlinopathy patients carrying a nonsense mutation." (PMID 38891760, 2024). "LGMD2B (Dysferlinopathy), caused by variants in the DYSF gene, is marked by early weakness and atrophy of the pelvic and shoulder muscles, generally without respiratory or cardiac involvement." (PMID 39596609, 2024). "Detection of ferlin deficiency in muscle or blood and identification of mutations in the DYSF gene are the main tools for diagnosing dysferlinopathy." (PMID 38903757, 2024). "A Polish study performed WES on 73 patients clinically diagnosed with LGMD, identifying pathogenic DYSF variants causing LGMD type 2B or a dysferlinopathy subtype of LGMD in 6 cases (8%)." (PMID 38539162, 2024).
dysferlinopathy (continued). "In summary, this study demonstrates for the first time that DYSF double mutations were associated with the development of dysferlinopathy." (PMID 38903757, 2024). "Dysferlinopathies are a clinically heterogeneous group of muscular dystrophies caused by gene mutations resulting in deficiency of the membrane-associated protein dysferlin." (PMID 39123261, 2024). "This study confirmed the applicability of ataluren treatment to dysferlinopathy patients with nonsense mutations in DYSF." (PMID 38903757, 2024). "Dysferlinopathy (caused by mutations in the DYSF gene) is a focused disease for three projects led by three companies (two in clinical trial phase I/II, one in the preclinical phase)." (PMID 38488469, 2024). "Dysferlinopathy, caused by a dysferlin gene mutation, usually presents in late adolescence with muscle weakness; the degenerative muscle changes are often accompanied by inflammatory infiltrates, resulting in misdiagnosis as PM." (PMID 38125829, 2023). "Dysferlinopathies are a group of autosomal recessive muscular dystrophies caused by pathogenic variants in the DYSF gene." (PMID 37239109, 2023). "Despite the rarity of such variants in DYSF, their evaluation should be included in cases where dysferlinopathy is highly expected and only one P/LP DYSF variant has been identified." (PMID 36983702, 2023). "In conclusion, our mouse model Dysf p.Y1159X/p.Y1159X recapitulated most aspects of the phenotype of previous dysferlin-deficient mouse models and dysferlinopathy patients." (PMID 37239109, 2023). "Dysferlinopathy, caused by a dysferlin gene mutation, usually presents in late adolescence with muscle weakness, degenerative muscle changes are often accompanied by inflammatory infiltrates, often resulting in a misdiagnosis as polymyositis." (PMID 38125829, 2023). "Dysferlinopathy is an autosomal recessively inherited muscular dystrophy caused by variants in the DYSF gene (OMIM: 603009) that predominantly affects skeletal muscle and results in progressive muscle weakness and wasting." (PMID 36983702, 2023). "The gait analysis in the dysferlin-deficient mouse model thus makes it possible to bring new data to the dysferlinopathies phenotype." (PMID 37239109, 2023). "These research avenues involve not only symptomatic treatments but also treatments such as exon skipping, myoblast transplantation, and gene editing, which treat the root cause of dysferlinopathy by restoring dysferlin protein expression." (PMID 37762951, 2023). "It is therefore essential to better characterize the pathology mechanisms of dysferlinopathies in order to carry out long-term phenotypic studies in dysferlin-deficient animal models." (PMID 37239109, 2023). "In this report, we identified a 17‐year‐old male diagnosed with dysferlinopathy who had a homozygous mutation in the DYSF gene." (PMID 36464789, 2023). "Dysferlinopathies are a group of autosomal recessive (AR) muscular dystrophies caused by mutations in the dysferlin gene (DYSF, MIM: 603009)." (PMID 36464789, 2023). "The most common clinical diagnoses associated with dysferlinopathy are limb–girdle muscular dystrophy R2 dysferlin related (formerly LGMD2B) and Miyoshi myopathy (MMD1)." (PMID 36983702, 2023). "Dysferlinopathy is caused by mutations in the DYSF gene located on chromosome 2p13.2, which spans a genomic region of approximately 233 kb and comprises 55 exons." (PMID 37974208, 2023). "In the past, desmoplakin (DYSF) has been studied as one of the most common subgroups causing dysferlinopathy (autosomal recessive limb-girdle muscular dystrophy)." (PMID 37226132, 2023). "Mutations in the DYSF gene, which encodes the dysferlin protein, cause autosomal recessive muscle disorders known as dysferlinopathies." (PMID 37686363, 2023).
dysferlinopathy (continued). "The membrane-repairing function in dysferlin-deficient myofibers can be recovered in dysferlinopathy models by expressing a “mini-dysferlin” peptide or myoferlin, another ferlin family protein, but these approaches do not arrest muscular degeneration." (PMID 35203715, 2022). "Dysferlinopathy encompasses a group of rare muscular dystrophies caused by recessive mutations in the DYSF gene." (PMID 35725460, 2022). "Dysferlinopathy is a group of autosomal recessive inherited myopathies caused by mutations in the DYSF gene." (PMID 36203997, 2022). "The identification of a mechanism of pathogenesis for DYSFPMMs is likely to aid clinicians in the diagnosis of individuals with dysferlinopathy through the (re)classification of known DYSF missense variants as pathogenic." (PMID 35028538, 2022). "Dysferlinopathy refers to a group of muscle diseases with progressive muscle weakness and atrophy caused by pathogenic mutations of the DYSF gene." (PMID 36203997, 2022). "Dysferlinopathy is an autosomal recessive neuromuscular disorder caused by mutations in the dysferlin gene, DYSF, leading to a deficiency of functional dysferlin, a protein that is highly expressed in muscle and that is essential in membrane repair." (PMID 35373496, 2022). "Mutations in the gene DYSF encoding dysferlin (OMIM#603009) are responsible for a group of autosomal recessive muscular dystrophies known as dysferlinopathies with onset commonly between the second and third decade of life." (PMID 36012197, 2022). "Dysferlinopathies are muscular dystrophies caused by recessive loss-of-function mutations in dysferlin (DYSF), a membrane protein involved in skeletal muscle membrane repair." (PMID 35028538, 2022). "Dysferlinopathy is a rare, autosomal recessive muscular dystrophy caused by mutations in the DYSF gene, which encodes the skeletal muscle protein dysferlin." (PMID 35359643, 2022). "Dysferlinopathies are a clinically heterogeneous group of muscular dystrophies caused by a genetic deficiency of the membrane-associated protein dysferlin, which usually manifest post-growth in young adults." (PMID 36613515, 2022). "Dysferlinopathy is an autosomal recessive muscular dystrophy caused by pathogenic variants in the DYSF gene, which is located on chromosome 2p13 and spans a genomic region of over 230 kbp consisting of 55 exons." (PMID 36319958, 2022). "Compound heterozygous DYSF gene mutations leading to dysferlinopathy had been reported in the literature." (PMID 35273475, 2022). "We reviewed the clinical and pathological data as well as the molecular characteristics of 26 Chinese patients with dysferlinopathy screened by immunohistochemistry staining and pathogenic variants in DYSF genes." (PMID 36319958, 2022). "Dysferlinopathy includes an autosomal recessively inherited group of Muscular Dystrophies caused by mutations in the DYSF gene, located on chromosome 2p13, codifying dysferlin protein." (PMID 36012197, 2022). "Dysferlinopathy is an autosomal recessive muscular dystrophy caused by pathogenic variants in the dysferlin (DYSF) gene." (PMID 36319958, 2022). "Dysferlinopathy, caused by mutation in the DYSF gene, is a family of autosomal recessive muscular disorders with distinguishing clinical features." (PMID 36203997, 2022). "Dysferlinopathy is muscular dystrophy caused by the deficiency of dysferlin protein coding by the DYSF gene." (PMID 36319958, 2022). "Mutations in dysferlin (dysferlinopathies), which cause progressive Miyoshi myopathy and limb girdle dystrophy type 2B, promote the infiltration of pro-inflammatory immune effector cells comprised mainly of macrophages." (PMID 35625891, 2022). "We developed a therapeutic pipeline to identify small molecules capable of restoring function to loss-of-function DYSF patient missense mutations (DYSFPMMs), which represent 30%–40% of dysferlinopathy mutations." (PMID 35028538, 2022).